MMP9 (matrix metallopeptidase 9)
Diseases named in the same sentence as MMP9 in open-access papers (continued):
Sharing a sentence is not in itself a finding about the gene and the disease.
colitis (119 papers, 2010 to 2026). Inflammation of the colon. "Some studies have suggested that in mouse models of acute and chronic dextran sulfate sodium (DSS)-induced colitis and acute 2,4,6-trinitrobenzene sulfonic acid-induced colitis, the parameters associated with chronic colitis in MMP-9 knockout mice are similar." (PMID 39712025, 2024). "The alteration of ECM in IBD is characterized by inflammatory mediators and activated matrix metalloproteinase‐9 (MMP9), which increases intestinal permeability, epithelial apoptosis and loss of goblet cells in colitis in humans." (PMID 37279179, 2023). "Under these conditions, the increased accumulation of Aβ in the brain caused by DSS colitis was suppressed by the MMP-9 inhibitor." (PMID 36922861, 2023). "MMP-9 deficient mice have reduced inflammation and intestinal tissue damage and were protected against STm induced colitis." (PMID 35733975, 2022). "CLDN-1 regulates colonic epithelial cell differentiation in a Notch and Akt-dependent manner and promotes colitis severity by regulating MMP-9 and p-ERK signaling, while impairing colitis-associated injury/repair." (PMID 35571126, 2022). "Our analysis revealed some diagnostic value of both serum TIMP-1 and MMP-9 in distinguishing children with left-sided colitis from those with right-sided colitis." (PMID 35566780, 2022). "For example, a recent study reported that MMP-9 was found to reduce reactive oxygen species and DNA damage in colitis-associated cancer, suggesting its protective role in the intestine." (PMID 35563751, 2022). "MMP9 has been implicated in the pathogenesis of colitis, with MMP-9−/− mice challenged with DSS having reduced inflammation and mucosal injury, whilst in Caco2-BBE cells, MMP-9 inhibited cell attachment and wound healing." (PMID 32429425, 2020). "However, it has also been reported that MMP-9 restricts the accumulation of reactive oxygen species and DNA damage in colon, and thus inhibits the occurrence colitis-associated cancer." (PMID 38448514, 2024). "Moreover, MMP9 has been implicated in the degradation of TJ proteins, leading to increased intestinal permeability and exacerbating colitis." (PMID 38474712, 2024). "MMP-9 is also causal in the establishment of colitis in mice." (PMID 37658104, 2023). "uPA-mediated signaling (Timp1-, Mmp3-, Mmp9-centered sub-networks) controls macrophage phagocytosis in intestinal inflammation, and uPA receptor deficiency leads to marked aggravation of experimental colitis in mice." (PMID 36901742, 2023). "Recent work suggests that MMP-9 upregulation is a consequence of intestinal inflammation, which is in contradiction with a previous investigation that suggests its causative implication in an experimental model of colitis." (PMID 33802197, 2021). "Both MMP-9-/- mice and WT littermates developed severe acute colitis after DSS administration with loss of body weight, higher disease activity index (DAI), increased colon/weight length ratio, and elevated macroscopic damage score compared to corresponding control mice." (PMID 30181895, 2018). "Animal studies have been conducted to investigate the causal role of MMP-9 in experimental colitis." (PMID 28561062, 2017). "Studies have demonstrated that MMP-9 expression is significantly elevated in patients with colitis, which is related to disease severity, suggesting its pro-inflammatory role in the inflammatory response." (PMID 40529132, 2025). "LB101 alleviated DE with colitis by suppressing MMP-9 expression and increasing tight junction protein with the regulation of gut microbiota-involved NF-κB signaling." (PMID 38885258, 2024). "Considering the role of lactate/GPR81 signaling in modulating MMP-9 expression and the disruption of TJ proteins in IECs, we further evaluated the protective effect of this axis on intestinal barrier function in colitis." (PMID 38474712, 2024).
colitis (continued). "In the intestinal mucosa of IBD patients, mice, and dogs, MMP-9 has been shown to promote the development of colitis." (PMID 39712025, 2024). "The immunofluorescence analysis of colons from the Gpr81−/− colitis mice also showed a significant accumulation of MMP9." (PMID 38474712, 2024). "Studies have identified that MMP9 plays a significant role in modulating inflammatory processes and tissue remodeling in colitis." (PMID 38474712, 2024). "MMP9 has been identified as a biomarker of intestinal inflammation and is known to exacerbate colitis severity by increasing the permeability of intestinal epithelial TJs." (PMID 38474712, 2024). "Inhibition of both CTSB and CTSD has been shown to ameliorate DSS colitis and overexpression of MMP-9 to aggravate DSS and infectious colitis." (PMID 39200138, 2024). "The expression of S100a9, S100a8, Lcn2, Il1f9, Mmp8, and Mmp9 were significantly increased in CD45+ cells from Il17b-/- colitis mice (P < 0.05)." (PMID 36814913, 2023). "Previous studies have also indicated the potential significance of epithelial cell-expressed MMP9 in colitis development, through its involvement in regulating cell-matrix interactions and wound healing." (PMID 37507767, 2023). "Collectively, these data suggest that acute colitis increases neutrophils in the blood followed by increased neutrophils in the brain resulting in increased MMP-9 activity and Aβ accumulation." (PMID 36922861, 2023). "This is in fact consistent with previous research that showed that the isolated Lupinus MMP-9 inhibitor is effective in reducing inflammation and lesions in animal models of induced colitis and cancer development." (PMID 35911116, 2022). "MMP-9 is the most important protease in relation to colitis, and it is significantly overexpressed in both human and animal models of IBD." (PMID 35054518, 2022). "MMP9 is predominantly upregulated in animal models of colitis and plays a major role in driving gut inflammation in both infectious and chemical-induced colitis." (PMID 35620197, 2022). "In a mouse model of colitis-associated CRC, the NF-κB mediated inflammatory reaction promotes protein expression of cyclin D1, phosphorylated ribosomal protein S6 and MMP-9 in the colon tissues of these mice, which plays a beneficial role in CRC progression." (PMID 36776395, 2022). "Previous studies suggest that both MMP-2 and MMP-9 are mediators of tissue damage; the first ones maintain the intestine barrier function and the second ones participate in colitis." (PMID 36140716, 2022). "When administered orally, isolated deflamin reduced colitis lesions, whilst inhibiting MMP-9 activity in mice." (PMID 35631241, 2022). "In mice models of colitis, it significantly inhibited colonic MMP-9 activities, whilst reducing inflammation and colitis-induced lesions, when administered orally as a lupin seed extract or as a food additive to wheat cookies." (PMID 36551666, 2022). "A previous study indicated intestinal MMP9 levels were increased in patients with inflammatory bowel disease and in mice with colitis induced by dextran sodium sulfate." (PMID 36552443, 2022). "MMP9 and MMP2 double-deficient susceptible mice are resistant to STm-induced colitis demonstrating that MMP-9 overrides the protective effect of MMP-2 in mediating inflammation and tissue damage." (PMID 35733975, 2022). "In acute TNBS-induced colitis in mice, decreasing the up-regulated colonic MMP-9 expression during IBD progression attenuated experimental colonic inflammation." (PMID 35766160, 2022). "In a DSS-induced colitis mouse model, not only MMP-9 activity but also chymase activity was significantly increased in the colitis lesions." (PMID 36289761, 2022).
colitis (continued). "Previous studies have shown that in animal models of colitis, MMP-9 was upregulated and played an important role in the development of intestinal inflammation." (PMID 33826658, 2021). "It has been also found that MMP-9 knockout mice are resistant to the development of experimental colitis." (PMID 33800267, 2021). "In the molecular docking model, the structure of mangiferin showed a high binding potential with TNF-α and MMP-9 and a reduced colonic injury partly through attenuating the activity of TNF-α and MMP-9 in the colitis model." (PMID 34066494, 2021). "MMP-9 expressed by epithelial cells mediates inflammation during colitis by modulating cell-matrix interaction and wound healing and simultaneous increasing in proinflammatory cytokine Kc." (PMID 31437166, 2019). "Epithelial-derived MMP-9 is an important mediator of tissue injury in colitis, whereas MMP-2 protects against tissue damage and maintains gut barrier function." (PMID 31437166, 2019). "In colitis associated with inflammatory bowel disease, epithelial and fecal MMP-9 levels correlate with severity of colitis." (PMID 30227886, 2018). "In this study, acute colitis was induced in co-housed MMP-9-/- mice (n = 10) and their wild-type (WT) littermates (n = 10) via oral administration of 3% dextran sodium sulfate (DSS) for 7 days followed by 2 days of regular drinking water." (PMID 30181895, 2018). "Mmp9 is also elevated in DSS colitis and has been shown to contribute to the severity of colitis by increasing intestinal epithelial TJ permeability." (PMID 29566748, 2018). "The severity of DSS- or TNBS-induced colitis obviously decreased in MMP9−/− mice, and inhibition of MMP9 can also alleviate intestinal inflammation." (PMID 29354126, 2017). "First, potential differences between WT and MMP-9−/− mice after induction of acute colitis were studied." (PMID 28561062, 2017). "Second, since IBD is characterized by a chronic disease course with tissue remodelling and fibrosis as important complications, we additionally studied the effect of MMP-9 gene KO on chronic DSS-induced colitis and fibrosis." (PMID 28561062, 2017). "As expected, mice with acute DSS-induced colitis had significantly increased expression of Mmp3, Mmp8 and Mmp9 compared to control mice." (PMID 28561062, 2017). "Taken together, our data demonstrated that modulation of ROS by procyanidin provided a potential method for colitis treatment, downregulating the expression of MMP9, the activation of NF-κB signaling, and the NLRP3 inflammasome at the same time." (PMID 29354126, 2017). "In previous studies, zingerone decreased the activity of NF-κB, and the protein levels of NF-κB and MMP-9 were downregulated in colitis models." (PMID 27323807, 2016). "In MMP-9 knock-out mice, DSS-induced colitis and the associated increase of intestinal permeability are attenuated." (PMID 27999328, 2016). "DSS-induced colitis studies have proved that MMP-9 activity increases in homogenates of colonic mucosa in UC and is dependent on TNF-alpha." (PMID 27034654, 2016). "The naturally occurring coumarin, 4-methylesculetin, showed comparable effects to sulphasalazine and prednisolone in TNBS induced colitis where it was able to inhibit MMP-9." (PMID 25948887, 2015). "We assessed the effect of MMP9 inhibition on established colitis by starting treatment with the mouse-specific antibody AB0046 after a 5-day course of DSS administration via the drinking water." (PMID 25961845, 2015). "It was also shown that the gelatinases play opposing roles in intestinal inflammation where MMP-9 can potentiate colitis but MMP-2 participates in maintaining epithelial barrier function to prevent the initiation of colitis." (PMID 25948887, 2015). "A combination of the antibiotic minocycline and the probiotic E. coli Nissle 1917 was shown to improve recovery form DSS induced colitis in mice including improved ratio of beneficial/harmful bacteria and reduced MMP-9 expression." (PMID 25948887, 2015).
colitis (continued). "When investigating the effect of MMP-9 on the colonic epithelial barrier in a model of colitis, it was found that MMP-9−/− mice had increased goblet cell numbers and increased MUC2 expression." (PMID 25948887, 2015). "A recent study showed that inhibition of PI3Kγ had anti-inflammatory effects in TNBS induced colitis which resulted in increased Treg response and decreased NF-κB mediated expression of MMP-9 and other inflammatory mediators." (PMID 25948887, 2015). "On the other hand, Castaneda and colleagues demonstrated that MMP-9−/− mice exposed to DSS or salmonella had a significantly reduced severity of colitis." (PMID 25890182, 2015). "Calcium supplementation has shown benefit in reducing epithelial permeability and inflammation in the intestine through reduced expression of MMP-9, -10, and -13 in HLA-B27 transgenic rat model of colitis." (PMID 25948887, 2015). "Upregulation of claudin-1 following DSS induced colitis results in an upregulation of MMP-9 which triggered Notch signalling resulting in decreased MUC2 expression through decreased goblet cell differentiation." (PMID 25948887, 2015). "A group studying Citrobacter rodentium-induced colitis in mice found that MMP-9 was upregulated in the model." (PMID 25948887, 2015). "Subsequent detailed analysis revealed that colitis severity was coupled with elevated levels of antimicrobials like Lcn2, which stabilized the pro-inflammatory endopeptidase MMP-9 in the intestinal milieu." (PMID 24465207, 2014). "Although MMPs are secreted by a variety of cell types, such as fibroblasts, epithelial cells, endothelial cells, neutrophils, macrophages, and lymphocytes, MMP-9 is predominantly expressed in epithelial cells and in inflammatory cells during colitis." (PMID 24465207, 2014). "Accumulation of Lcn2 stabilizes the metalloproteinase MMP-9 via extracellular binding, which further aggravates the colitis." (PMID 24465207, 2014). "In other animal models of IBD,MMP-9 is indispensible for establishment of inflammation in the dextran sodiumsulphate (DSS) colitis model throughsuppression of epithelial wound healing and goblet cell differentiation." (PMID 22694805, 2012). "We therefore sought to determine thecontribution of MMP-9 to the pathogenesis of Citrobacterrodentium-induced colitis and its effects on gut microbiomehomeostasis." (PMID 22694805, 2012). "MMP9, a gelatinase, that showed a 7-fold up-regulation in diseased samples in our study is an important mediator of tissue injury in colitis and is up-regulated in sputum samples of CD patients." (PMID 20444268, 2010). "Furthermore, a study on lupin protein concentrate (LPC) enriched with deflamin, an inhibitor of MMP-9 (an enzyme linked to inflammatory bowel diseases), showed that LPC significantly reduced colitis severity in a TNBS-induced colitis mouse model." (PMID 40507018, 2025). "Inhibition of MMP-9 activity may contribute to reducing the damage and inflammatory response of colitis." (PMID 40529132, 2025). "Considering these facts about MMP-9, we decided to check whether the administration of compounds 7b, 10b, and 13b for 16 days in the experimental colitis altered the MMP-9 tissue concentrations." (PMID 40283981, 2025). "Experimental models of colitis have shown that the targeted deletion or pharmacological inhibition of MMP9 can mitigate colonic damage, indicating that MMP9 may serve as a viable therapeutic target for UC." (PMID 38474712, 2024). "MMP9 is also a significant tissue damage mediator in colitis." (PMID 39474054, 2024). "In our study, we found that the lactate/GPR81 axis could limit experimental colitis by inhibiting TNF-α/NF-κB/MMP9 signaling." (PMID 38474712, 2024). "Our findings indicate that lactate/GPR81 signaling protects the integrity of the intestinal epithelial barrier and may alleviate colitis symptoms, possibly by inhibiting the activation of NF-κB/MMP9 pathways." (PMID 38474712, 2024).
colitis (continued). "Furthermore, Gpr81 knockout resulted in increased protein expression of MMP9 and decreased expressions of Claudin-1, ZO-1, and Occludin in the colitis mice." (PMID 38474712, 2024). "We also observed that the expression of MMP9 was dramatically upregulated at both the mRNA and protein levels in the cellular and mouse models of colitis, and knockout of Olfm4 further upregulated the expression of MMP9 in LPS-stimulated cells and in the colon of DSS-treated mice." (PMID 37151883, 2023). "In vitro studies revealed that MMP-9 derived from intestinal epithelial cells (but not from neutrophils) plays a key role in the pathogenesis of colitis by inhibiting epithelial cell-ECM interaction and wound healing; MMP-9 knockout mice are more resistant to various types of induced colitis." (PMID 38288108, 2023). "To explore whether MMP9 mediated the regulatory effects of OLFM4 on colitis in mice, we transfected Olfm4-/- mice and WT littermates with recombinant adeno-associated virus-shMMP9 (AAV-shMMP9) or control vectors (AAV-shNC) through tail vein injection." (PMID 37151883, 2023). "This suggests that chymase-dependent MMP-9 activation might play a crucial role in the development of DSS-induced colitis." (PMID 36289761, 2022). "Inhibited TNF-α, iNOS, MMP-3, MMP-9 mRNA Expressions in colonic tissue of a colitis model." (PMID 35208860, 2022). "MMPs comprise a family of zinc-dependent endopeptidases with a well-recognized key role in intestinal inflammation, particularly gelatinase MMP-9, which has been shown to be up-regulated in human colitis and other IBDs and is positively correlated with disease severity." (PMID 35631241, 2022). "Moreover, the increase in MMP-9 levels after incubation of an extract of colitis lesions was completely prevented by treatment with a chymase inhibitor." (PMID 36289761, 2022). "DSS-induced colitis was found to be significantly attenuated in MMP-9-deficient mice, but not in MMP-2-deficient mice." (PMID 36289761, 2022). "Additionally, and in agreement with our results, it had already been described that VIP-signaling induces a reduction in MMP9 expression in rodent models of colitis and lung damage as well as in fibroblastic synoviocytes from patients with osteoarthritis." (PMID 34944693, 2021). "Moreover, recent evidence demonstrates that MMP9 induced increase in intestinal epithelial TJ permeability contributes to the severity of experimental DSS colitis." (PMID 33300279, 2021). "Here, we have shown novel MMP-2 and MMP-9 inhibitory activity from protein components of lupine, which were found to be active in vivo when administered orally, whilst alleviating the symptoms of induced colitis in mice." (PMID 34948082, 2021). "The prevention of intestinal mucosal barrier injury observed in pioglitazone-treated mice with colitis was also associated with increased expressions of tight junction proteins and reduced protein levels of TNF-α, IL-6, and MMP9, which are soluble mediators controlled by the ERK-NF-κB." (PMID 31989391, 2020). "A later study utilizing three different mouse models of colitis indicated that MMP-9 upregulation was a consequence, rather than a cause, of intestinal inflammation." (PMID 31461880, 2019). "Based on animal studies, MMP-9 was viewed as an appropriate target for modulating colitis." (PMID 31461880, 2019). "MMP9 was significantly elevated with the development of DSS-induced colitis in colonic tissues." (PMID 29354126, 2017). "In addition, we use two peptide inhibitors with proven efficacy towards MMP-9 in an acute DSS-induced colitis model in three different set-ups: multiple dose prophylactic and therapeutic schemes, and continuous infusion via osmotic pumps." (PMID 28561062, 2017).